IDO1 (indoleamine 2,3-dioxygenase 1)
Diseases named in the same sentence as IDO1 in open-access papers (continued):
Sharing a sentence is not in itself a finding about the gene and the disease.
cancer (continued). "Similarly, in our study we found an increase of IDO1 expression in primary carcinomas with good prognosis." (PMID 24495478, 2014). "We were interested in the immunomodulatory effects of 1-D-MT in IDO1-positive human cancer cells." (PMID 21625531, 2011). "Interestingly, the 1-D-MT-mediated upregulation of IDO1 mRNA in many IDO1-negative cancer cells was differentially dependent of the concentration of IFN-γ that was used to induce de novo expression of IDO1." (PMID 21625531, 2011). "Elucidating the interactions between IDO1 and other pathways, as well as the mechanisms behind the constitutive activation of IDO1 in cancer, is crucial for understanding other pathways that may compensate for IDO1 function and developing effective treatment strategies." (PMID 41129671, 2026). "However, the IDO1 protein level was increased in most of the inhibitor-treated cells with an FC >2 compared to the control represented by the basal expression of the IDO1 protein in the cancer cell line." (PMID 41262240, 2025). "In this work, we show that this strategy can be applied with success in DCs derived from the THP-1 acute monocytic leukemia cell line as a model for the delivery of silencing strategies targeting the IDO1 gene that could enhance immunomodulation for cancer therapeutics." (PMID 40848064, 2025). "Notably, IDO2-dependent B cell inflammatory states and IDO1-regulated Tregs may both play roles in cancer progression." (PMID 41035912, 2025). "However, chronic STING activation may have undesired opposite effects, such as enhanced cancer cell survival and immunosuppressive IDO1 induction." (PMID 38831013, 2024). "Such conjugates show promising activity against cancer-associated carbonic anhydrase IX (CA IX), hypoxia-inducible factor-1 (HIF-1), nicotinamide phosphoribosyltransferase (NAMPT), cyclooxygenase (COX), lipoxygenase (LO), and indoleamine-2,3-dioxygenase-1 (IDO1)." (PMID 39407644, 2024). "Therefore, IDO1 inhibitors may be particularly beneficial to patients with IBD and at high risk of developing cancer, in particular those carrying previously identified high risk DOCK2 mutations." (PMID 39242821, 2024). "However, IDO-1 inhibitors might dampen T cell-mediated immunity by limiting tryptophan metabolism, and it was crucial to target IDO-1 inhibitors to cancer cells specifically." (PMID 36798123, 2023). "In fact, many scRNAseq data sets show overlapping patterns of myeloid IL4i1 and IDO1 expression in the TME raising the possibility that (i) this is a universal response in the chronic inflammation of cancer and (ii) that multiple factors may control the expression of both enzymes." (PMID 37196768, 2023). "Therefore, IDO1 is considered an attractive target for cancer immunotherapy." (PMID 37630387, 2023). "Indeed, it has been shown that a cocktail of IDO1 inhibitors and immunotherapeutic drugs, including agents targeting cytotoxic T lymphocyte-associated protein 4 (CTLA4) or PD-1, displays a synergistic effect in combating cancer." (PMID 37895133, 2023). "Thus, therapeutically targeting IDO1 may represent a promising approach for improved treatment of diverse cancers, particularly when combined with ICB." (PMID 37945606, 2023). "Therefore, inhibiting IDO1 has become a new target for cancer therapy." (PMID 36983678, 2023). "Therefore, targeting IDO1 for the treatment of cancer could be considered as an immunosuppressive-targeted strategy." (PMID 35572960, 2022). "However, the role of IDO1 in clinical cancer studies is still conflicting." (PMID 36212460, 2022). "Besides, IDO1 expression is correlated with a poor prognosis, shorter overall survival, and chemoresistance in different cancers, corroborating the concept that a treatment strategy of IDO1 blockade may have antitumor effects." (PMID 35371054, 2022).
cancer (continued). "Therefore, it is possible that part of the therapeutic success of carfilzomib lies in its ability to reach all cell types in the blood and tissues where it may inhibit IDO1 expression, contributing to its anti-cancer efficacy." (PMID 35371018, 2022). "Consequently, the downregulation of IDO1 in DC is a vital mechanism of immunological changes induced by curcumin which could be used in cancer therapy." (PMID 35918736, 2022). "Indeed, a wide range of studies and clinical trials have been performed to modulate KP enzyme activities as cancer therapeutic strategies, mainly related to IDO1, TDO2, KAT and KYNU, that are too numerous to list here, but the following are useful reviews and accounts." (PMID 36286592, 2022). "However, links between IDO1 and ferroptosis, which may have key roles in cancer cell survival have yet to be recognized." (PMID 35245456, 2022). "Therefore, the simultaneous inhibition of ARG1 and IDO1 and/or TGFβ signalling could constitute a compelling anti-cancer therapeutic strategy." (PMID 34685679, 2021). "However, the specific role of IDO1 in cancer cells, particularly HCC, remains to be clarified." (PMID 34769098, 2021). "CXCL1, LCN2, S100A8, and IDO1 may play essential roles in cancer progression." (PMID 34306038, 2021). "Considering the critical roles of IDO1 in cancer metabolism and immune modulation, we envisioned that IDO1 holds potential as an effective biomarker to identify the cancer-immune set point, which might help to specify the right patient at the right time for IDO1-blockade combination therapy." (PMID 34148865, 2021). "Therefore, in cancer with an overexpression of IDO1/TDO2, increased Trp catabolism could lead to the depletion of its serum concentration and the accumulation of Kyn metabolites, which enhanced cancer scenario." (PMID 33466323, 2021). "In addition to IDO1, high levels of KYN are implicated in cancer progression." (PMID 34445444, 2021). "Therefore, the appropriate regulation of the phosphorylation of ITIMs of IDO1, leading to either enhancing or terminating the expression of IDO1, may provide some innovative strategies in treating malignant tumors." (PMID 35003126, 2021). "Besides an indirect impact of IDO1 on cancer cells, it excretes its own direct effect." (PMID 34071442, 2021). "Therefore, IDO inhibitors in combination with ICI-based immunotherapies or standard treatments deserve thorough investigations in cancer, and more clinical studies with immune monitoring are required to evaluate the impact of IDO-1-targeting on modulating the immunological landscape of TME." (PMID 34685679, 2021). "After the discovery that placental IDO1 was the key enzyme mediating immune suppression in maternal–foetal tolerance in 1998, the research focus was expanded to examine whether the KP was involved in immune evasion and cancer." (PMID 34680327, 2021). "Therefore, a full understanding of the expression of IDO1 and biological function may provide more effective immunotherapeutic approaches for a wide range of malignant tumors." (PMID 35003126, 2021). "The immunoregulatory molecule indoleamine 2,3-dioxygenase 1 (IDO1)—which catalyzes the first, rate-limiting step of Trp degradation through the kynurenine (Kyn) pathway—is highly expressed in many types of human cancers and is generally associated with poor prognosis." (PMID 32536910, 2020). "Furthermore, IDO1 expression is very heterogeneous, even within a single cancer entity." (PMID 31819194, 2020). "The IDO1/CD8A classifier may be suitable for use in the prediction of cancer development." (PMID 33425745, 2020). "In addition, UCEC contained a higher TMB level and IDO1 expression than other four female cancers." (PMID 32227579, 2020). "Thus, inhibition of IDO1 has emerged as an attractive strategy for cancer immunotherapy." (PMID 30777103, 2019). "Increased ARG1 activity might lead to IDO1-dependent Trp starvation in cancer cells." (PMID 31354721, 2019).
cancer (continued). "Notably, IDO1 is overexpressed in a range of cancer tissues." (PMID 31195673, 2019). "Although less studied, IDO2 has been found to be overexpressed in some human tumors, to functionally enable IDO1-dependent Treg suppression, and to underpin B cell–mediated autoantibody production, which is important in the development of certain cancers, such as squamous cell carcinomas." (PMID 30806743, 2019). "Besides, IDO1 inhibitors are promising candidates for cancer immunotherapy." (PMID 31719837, 2019). "Additionally, IDO1 is reported to be highly expressed in a wide variety of human cancers." (PMID 31391111, 2019). "Overall, in this study we discovered a series of IDO1 inhibitors with a novel scaffold using the structure-guided drug design approach, which provides a useful starting point and information for the further development of cancer therapy and the related chemical biology studies." (PMID 29651242, 2018). "Interestingly, in an experimental study, IFN-γ exhibited its antiproliferative effects only in cancer cell lines in which it upregulated IDO1 expression with a consequent tryptophan deprivation; suggesting a possible direct antitumor effect of this enzyme in certain types of cancer." (PMID 30150994, 2018). "There are many pathologic diseases that are associated with increased IDO1 activity, including atherosclerosis, obesity, autoimmunity, major infections (e.g., community-acquired pneumonia, tuberculosis, listeriosis, influenza, HBV, HCV, HIV, sepsis), rejection of organ transplants, and cancer." (PMID 29445380, 2018). "Targeting IDO2 and TDO in addition to IDO1 may open new windows for cancer immunotherapy." (PMID 30068361, 2018). "A PET imaging tracer that is specific for IDO1 would allow noninvasive detection of IDO1 levels, which would have potential applications for variety of cancer detection and staging, and could also provide a new approach for predicting and monitoring the role of IDO1 in immunotherapy." (PMID 28159919, 2017). "Therefore, IDO1 has emerged as an attractive therapeutic target for cancer immunotherapy." (PMID 29120388, 2017). "IDO1 therefore represents a potentially important therapeutic target that could be used in conjunction with cART in HIV-infected patients or in conjunction with chemotherapy in cancer patients." (PMID 28066416, 2016). "In addition, a previous study reported that certain phytochemicals markedly reduce the IDO1 activity, and that this inhibition may at least in part explain their anti-cancer properties." (PMID 25376937, 2015). "IDO1 expression was also found to correlate with the basal phenotype common to ER- cancers and the high levels of kynurenine produced could result in reduced immunosurveillance of these cancers." (PMID 25091696, 2014). "Although IDO1 does not possess a transcriptional activity of its own like other substrates of CUL4BAhR, it is noteworthy that, in cancer tissues, IDO1 plays a proliferative action, and therefore, the putative CUL4BAhR-mediated degradation of IDO1 may result in antiproliferative activity." (PMID 25360135, 2014). "Carcinomas may create an immunosuppressive state via IDO1 expression." (PMID 22108515, 2012). "Pharmacological inhibition of Ido1 with PAL effectively mitigates these effects, positioning Ido1 as a promising therapeutic target for treating cancer cachexia." (PMID 42028912, 2026). "First, we evaluated the IDO1 catalytic inhibition by EPA, LIN, and NAV in the cancer cell lines after exposure to 1 μM of inhibitors for 24 h, by measuring Kyn levels in the culture supernatants." (PMID 41262240, 2025). "The strategic inhibition of tryptophan metabolism through interference with IDO1 and TDO enzymatic activity has emerged as a significant focus in cancer immunotherapy research." (PMID 40894232, 2025).
cancer (continued). "Cancer cells often overexpress SLC43A2, limiting methionine availability for T cells, and IDO1 hyperactivation promotes immunosuppression via kynurenine accumulation." (PMID 40475762, 2025). "Like its paralog IDO1, IDO2 expression is upregulated in most studied cancers, although some cancers show decreased IDO2 activity." (PMID 41035912, 2025). "The quantification of IDO-1 and IFN-γ can be helpful in the diagnosis of cancers and also in monitoring their treatment." (PMID 40710094, 2025). "Cell-type-resolved maps of IDO1, TDO, transporters, and System L remain incomplete; single-cell, longitudinal multi-omics in inflamed tissues and cancers are needed." (PMID 40868271, 2025). "Clinical studies highlight that the dysregulated expression of IDO1 and TDO2 significantly influences cancer prognosis." (PMID 41332472, 2025). "Several enzymes involved in the KYN pathway, including indoleamine 2,3-dioxygenase 1 (IDO1) and tryptophan 2,3-dioxygenase (TDO2), are upregulated in cancer cells and contribute to therapy resistance." (PMID 39997327, 2025). "Emerging research highlights crucial insights into precisely distinguishing Trp metabolism fluxes mediated by IDO1 and TDO, especially within the context of cancer progression and immune modulation." (PMID 40868271, 2025). "In summary, our findings reveal an immunoregulatory circuit in cancer, with STING monotherapy contributing to IDO1-induced immune evasion via the IFN-γ–IDO axis, which subsequently subdues T cell–mediated antitumor responses." (PMID 41129257, 2025). "Self-renewing CSC express high levels of indoleamine 2,3-dioxygenase 1 (IDO1) and TGFβ from a variety of cancer cell lines, both of which are key inducers of Treg cell recruitment and generation." (PMID 39184916, 2024). "Therefore, CD8+ T cell-derived IFN-γ could contribute to IDO1 expression in cancer cells." (PMID 38540186, 2024). "Remarkably, five genes (PDCD1LG2, CD48, IDO1, LAIR1, and PDCD1) were found to be present in both the cancer-immunity cycle inhibitors and checkpoint genes categories." (PMID 38540734, 2024). "IDO1 and IDO2 were found in various types of cancers, and their presence was related to resistance to therapy and lower survival." (PMID 39337426, 2024). "Enzymes, such as indoleamine-2,3-dioxygenase 1 (IDO1), IDO2, or tryptophan-2,3-dioxygenase, catalyze this, thereby modulating immunity and fostering cancer progression via tryptophan depletion and aryl hydrocarbon receptor activation." (PMID 38732512, 2024). "IDO1 and TDO2 are the initial Trp metabolizing enzymes of KP and are highly expressed in a variety of cancers." (PMID 38887298, 2024). "Phosphorylation of STAT3 is associated with increased PD-L1 expression on Treg cells and Indoleamine 2,3-dioxygenase 1(IDO1) on myeloid-derived suppressor cells, frequently observed in dedifferentiated cancer cells and infiltrating lymphocytes." (PMID 38646539, 2024). "Cancer cells take up tryptophan via SLC7A5 and SLC6A14 and, once inside the cell, tryptophan gets degraded by indoleamine-2,3-dioxygenase-1 (IDO1)." (PMID 38339256, 2024). "AHR is a ligand-activated transcription factor that mediates the immunosuppressive effects of IDO1/TDO-produced kynurenine metabolites, regulates transcriptional programmes in immune cells and affects cancer cell proliferation." (PMID 38831013, 2024). "Enzymes such as IDO-1, IDO-2, and tryptophan 2,3-dioxygenase degrade L-tryptophan to N-formyl-L-kynurenine and are overexpressed in cancer cells and MDSCs." (PMID 38474232, 2024). "IDO1 and GITR agonists/inhibitors are currently being investigated as potential targets for immunotherapy in several cancer subtypes." (PMID 39001353, 2024). "Results indicated high expression of IL4I1, TDO2, NIT2, and IDO1, while IDO2, ADI1, DDC, HPD, BHMT2 exhibited low expression in most cancers." (PMID 38691253, 2024).
cancer (continued). "Similar as observed for IDO1, α-PD-1 treatment can also induce IL4I1 upregulation in cancer patients, and IL4I1 is suggested to potentially constitute a resistance mechanism to immune checkpoint blockade." (PMID 39211039, 2024). "The T cell markers CD28 and FLT3LG expression decreased in cancer while FOXP3, IDO1, and ULBP2 expression increased." (PMID 39672307, 2024). "Upregulation of tryptophan catabolism by IDO1 and TDO2 is a well-described mechanism of cancer immune evasion." (PMID 38339226, 2024). "We found CD47 had strong correlation with CD274, LAG3, IDO1 and TNF receptor superfamily in pan-cancer(r > 0.2, p < 0.05)." (PMID 38720108, 2024). "Both IDO1 and TDO2 are responsible for the conversion of Trp to Kyn that block anti-cancer activity of cytotoxic T cells within TME." (PMID 39769192, 2024). "The immunoregulatory function of IDO1 is one also commonly exploited by tumors, and has additionally been ascribed to TDO expressed in the context of cancer." (PMID 39211039, 2024). "Taken together, although the field studying the role of IL4I1 in cancer immune escape is still in its relative infancy compared to that of IDO1, the pharmacological targeting of IL4I1 offers new prospects for the treatment of cancer patients." (PMID 39211039, 2024). "The importance of over-expression of the tryptophan catabolising enzymes IDO1 and TDO2 in solid cancers has been known for some time, with particular focus placed, until recently, on IDO1 as a potential target for cancer treatment." (PMID 39048947, 2024). "Subsequently, we also explored the correlation between the expression levels of LRP6 and the expression levels of common immune checkpoints in 33 cancers, such as SIGLEC15, IDO1, CD274, HAVCR2, PDCD1, CTLA4, LAG3 and PDCD1LG2." (PMID 38226972, 2024). "A recent study found the expression of IDO1 and IDO2 in many cancer types, including breast, colon, and endometrial cancers." (PMID 37408267, 2023). "This further underscores the significance of the IDO1 and COX-2 pathways, including PGE2 production, in modulating the immune response mediated by iNKT cells in the context of cancer." (PMID 37444608, 2023). "Furano[2,3-b]naphtho-4,9-dione 12b, isolated from Tabebuia avellanedae, shows a preference for inhibition of cancer cell growth over normal cells, with STAT3 inhibitory mechanisms proposed, while other FNQ natural products inhibit IDO1 (see Section 3.1.3)." (PMID 37446864, 2023). "For example, overexpression of IDO1, IDO2, and TDO2 results in drug resistance, enhanced metastasis formation, intense cancer cell proliferation, impeded apoptosis, and a poor prognosis for patients." (PMID 38201550, 2023). "Indeed, IDO1+ cells export kynurenines, which are imported by non-IDO1-expressing cells via solute carrier transporters, and these tryptophan catabolites are converted in metabolites with anti-ferroptotic activity, supporting local immunosuppression and cancer cell proliferation." (PMID 36161514, 2023). "Mechanistically, necrosis secondary to impaired efferocytosis stimulated IFN-γ-inducible expression of indoleamine 2,3-dioxygenase 1 (IDO1), culminating in immunosuppression and cancer development." (PMID 38283351, 2023). "The discovery that targeting IDO1 could subvert the protection from maternal immunity that a hemiallogeneic fetus requires for successful gestation was followed by demonstrations that inhibiting IDO1 could relieve T cell-directed immunological suppression in cancer." (PMID 37182174, 2023). "In specific, TIS is referred to as an 18‐gene signature (CCL5, GZMK, CD3D, CD3E, CD2, HLA‐DRA, IL2RG, NKG7, CIITA, CXCR6, LAG3, TAGAP, HLA‐E, CXCL13, IDO1, CXCL10, STAT1, and GZMB), which was related to the response to ICIs in various cancers." (PMID 37434432, 2023).